MEN1 (menin 1)
Diseases named in the same sentence as MEN1 in open-access papers (continued):
Sharing a sentence is not in itself a finding about the gene and the disease.
hyperparathyroidism (continued). "This family expands the phenotype associated with the c.1A > G pathogenic variant and highlights the importance of providing comprehensive assessment of MEN1 mutation carriers in families that at first blush may appear to have isolated hyperparathyroidism." (PMID 28736585, 2017). "For example, in a patient with previously-diagnosed hyperparathyroidism, MEN1 is a possible cause." (PMID 28965289, 2017). "Additionally, MEN1 mutations trigger familial isolated hyperparathyroidism." (PMID 28736585, 2017). "We present a case of a patient with MEN1 who presented with clinical symptoms of hyperparathyroidism." (PMID 40144450, 2025). "In MEN1-related hyperparathyroidism, parathyroidectomy or calcimimetics (e.g., cinacalcet) mitigate bone loss and skeletal complications." (PMID 41458551, 2025). "A 55-year-old man with a medical history of GERD esophagitis, esophageal stricture, and MEN1-related hyperparathyroidism was admitted to the hospital for chest pain and esophagitis." (PMID 37090344, 2023). "The remaining patients in this group were diagnosed using PET/CT with [11C]MET due to MEN1-related (7 patients) or sporadic primary (pHPT) hyperparathyroidism (25 patients)." (PMID 36615844, 2022). "In line with current knowledge, most of the patients in our cohort developed PHPT before the age of 50 (86.7%), and hyperparathyroidism was the earliest endocrine manifestation of MEN1 in 64% of them." (PMID 35407574, 2022). "Several genes have been established as containing disease-causing mutations for the familial PHPT: MEN1 gene for MEN1, RET gene for MEN2A, CASR gene for neonatal severe hyperparathyroidism, and CDC73 gene for HPT-JT." (PMID 35586626, 2022). "In known MEN1 kindreds, children and adolescents are recognized to have mild biochemical evidence of hyperparathyroidism with hypercalcemia prior to the onset of symptoms." (PMID 33716975, 2021). "MEN1 is an autosomal dominantly inherited disease characterised by hyperparathyroidism, gastro-enteropancreatic neuroendocrine (NET) and pituitary tumours, with associated other endocrine and non-endocrine tumours." (PMID 33543431, 2021). "In the case of MEN1, the additional main clinical features, such as hyperparathyroidism and enteropancreatic NET present in the proband or other family members, can help in the decision regarding genetic testing." (PMID 33543431, 2021). "Personal or familiar history of hyperparathyroidism or genetic syndromes associated with parathyroid carcinoma, like HPT‐JT and MEN1, should also raise clinical suspicion." (PMID 32884778, 2020). "Our study supports the trend of paradigm shift of reoperation in MEN1-related hyperparathyroidism patients from ‘surgical failure’ to ‘strategic staged operation’." (PMID 32606444, 2020). "MEN1 mutations also cause familial isolated primary hyperparathyroidism (FIHP), a milder condition causing hyperparathyroidism only." (PMID 32348957, 2020). "In this original study we describe and explain the rational of our peri-operative approach and management at MD Anderson Cancer Center of MEN1 patients with hyperparathyroidism." (PMID 30459713, 2018). "Testing is adviced if the familial history is suggestive of MEN1 or a second MEN1 feature is present, e.g., hyperparathyroidism." (PMID 30254610, 2018). "Despite the fact that hyperparathyroidism is usually the first manifestation of MEN1, the penetrance of these tumors is similar." (PMID 24213321, 2012). "The first clinical manifestation of MEN1 is hyperparathyroidism, mainly due to multiglandular hyperplasia, which usually affects more than 95% of all MEN1 patients." (PMID 21266030, 2011). "Historically, the vast majority of MEN1 patients have hyperparathyroidism at diagnosis." (PMID 41463062, 2025).
hyperparathyroidism (continued). "This syndrome was recently defined, after a germline nonsense mutation had been described in a patient affected by acromegaly and hyperparathyroidism, and in three out of six of her relatives who underwent testing, in the absence of MEN1 mutations." (PMID 35743266, 2022). "We studied the prevalence and phenotype of family members who manifested both genetic alterations (MEN1 and CDC73); individuals with both alterations presented with a prevalence of hyperparathyroidism of 50% (3/6) compared to 55% (6/11) with MEN1 mutation alone." (PMID 34889280, 2021). "Although these studies were conducted on patients with normal parathyroid glands, a similar pathophysiology may be applied to parathyroidectomy after MEN1-related hyperparathyroidism." (PMID 32606444, 2020). "Once we make this conceptual leap, then the question becomes how do we identify those MEN1 patients who may have a less aggressive manifestation of hyperparathyroidism and treat them less aggressively." (PMID 27402205, 2016). "Aside from disorders in the MEN1 gene, PA and hyperparathyroidism may concomitantly interact with each other." (PMID 24343173, 2015). "Carriers of MEN-1 mutations require regular screening at least in 3-year intervals regardless of the current presence of hyperparathyroidism from the second decade of life." (PMID 21318141, 2010). "It is therefore reasonable to suggest that younger patients with a functioning or non-functioning pNET have screening for hyperparathyroidism and a pituitary profile to assess if there is any suggestion of other MEN1 associated tumours; genetic screening can follow if indicated." (PMID 28965289, 2017). "This patient might have a MEN1 like phenotype, as she showed the clinical features typical of MEN1 syndrome (pancreatic neuroendocrine tumor, pituitary microadenoma and adrenal adenoma), despite the absence of hyperparathyroidism and MEN1 gene mutations." (PMID 24961548, 2014). "Where surgery has been noncurative or is not possible, cinacalcet may provide a medical alternative; this is supported by our study and a recent case report of a 30-year-old woman who maintained biochemical control after 1 year of cinacalcet for management of MEN1 hyperparathyroidism." (PMID 20585352, 2010). "For example, MEN1 typically involves tumors of the parathyroid, pancreas, and pituitary, while MEN2 includes medullary thyroid carcinoma, pheochromocytoma, and hyperparathyroidism." (PMID 40525079, 2025). "Genetic forms of PHPT include MEN1, MEN2 (RET gene), MEN4 (CDKN1B/p27 gene), and hyperparathyroidism-jaw tumour syndrome (CDC73 gene)." (PMID 40364143, 2025). "Recurrent hyperparathyroidism and a gastric NET at a young age led to a putative clinical diagnosis of MEN1, but the genetic study performed in 2004 (SSCP) was negative for this condition." (PMID 34889280, 2021). "Several responsible genetic germline changes associated with parathyroid tumors in familial syndromes, such as MEN1 in MEN 1, RET in MEN 2 A, and CDC73/HRPT2 in HPT-JS (hyperparathyroidism-jaw tumor syndrome), have been identified." (PMID 30104706, 2018). "MEN1, MEN2A and familial hyperparathyroidism are other inherited diseases which can present with hyperparathyroidism in childhood." (PMID 25241609, 2014). "On the other hand, MEN1 syndrome (multiple endocrine neoplasia type 1) can manifest during adolescence with prolactinoma in combination with hyperparathyroidism or pancreatic tumors; however, in the absence of other endocrine findings, MEN1 is less likely." (PMID 40599499, 2025). "The affected individuals exhibited PHPT without any clinical or biochemicalevidence of MEN1, MEN2, FHH, or hyperparathyroidism-jaw tumor syndrome, therebyfulfilling the diagnostic criteria for FIHP." (PMID 40893023, 2025).
hyperparathyroidism (continued). "A systematic review and meta-analysis compared the recurrence rate of PHPT after SPX and LPX in patients with MEN1-related PHPT, finding that the risks of recurrence, persistence of hyperparathyroidism, and reoperation for hyperparathyroidism after LPX are all significantly higher than those of SPX." (PMID 37795364, 2023). "MEN1/ZES occurs in 20–25% of all ZES patients and numerous studies have clearly established the fact that the presence of hyperparathyroidism in these patients (>95% at some point) results in increased BAO, MAO, fasting gastrin levels, and increased resistance to antisecretory drug therapy." (PMID 36900170, 2023). "MEN1 syndrome was considered because of the paternal grandfather’s parathyroid disease; however, his age at onset of hyperparathyroidism was quite late, and no other MEN1-related manifestations were present in the family." (PMID 31125088, 2019). "Because unrecognized MEN1 patients should not be explored, a diagnosis should be obtained before surgical exploration in patients with hyperparathyroidism." (PMID 21747852, 2011). "MEN1 hyperparathyroidism is invariably due to chief cell hyperplasia rather than a monoclonal adenoma." (PMID 20585352, 2010). "MEN1 is characterized by tumors of the parathyroid, entero-pancreatic, and anterior pituitary glands, with penetrance approaching 95% by the sixth decade of life, whereas MEN2 typically includes medullary thyroid carcinoma, pheochromocytoma, and hyperparathyroidism." (PMID 40525079, 2025). "In patients with familial PHPT, a negative testing for MEN1, potentially involves MEN2, MEN4, familial isolated PHPT, or hyperparathyroidism jaw-tumour syndrome." (PMID 40364143, 2025). "Notably, the disease exhibited characteristics of both MEN1 (non-secretory macroadenoma and adrenal tumor) and MEN2 (MTC), while hyperparathyroidism is common to both syndromes." (PMID 40476723, 2025).
parathyroid adenomas (72 papers, 2006 to 2026). "Conversely, other germline mutations predisposing to parathyroid adenomas, such as MEN1, CASR, and FHH, are rarely implicated in PC." (PMID 41568161, 2026). "Specifically, miR-4258 is markedly downregulated in parathyroid adenomas with MEN1 LOH, while miR-1301 and miR-664 are upregulated in parathyroid adenomas with MEN1 LOH or one inactivated MEN1 allele, respectively." (PMID 39336822, 2024). "The pattern of loss of heterozygosity (LOH) was assessed by fluorescence in situ hybridization (FISH) in one MEN1-associated parathyroid adenoma." (PMID 38244045, 2024). "In this study, we observed a complete loss of Menin expression in MEN1 parathyroid adenomas in all regions evaluable." (PMID 38244045, 2024). "A prevalent genomic aberration observed in parathyroid adenoma is the loss of heterozygosity of the MEN1 tumor suppressor gene, which governs cell growth and cell cycle." (PMID 37854190, 2023). "Loss of one MEN1 allele is found in 25%–40% of parathyroid adenomas, together with inactivating mutations of other alleles, which is an early event as it is identified in cases of small adenomas with mild hypercalcemia." (PMID 37223014, 2023). "Patient 2 subsequently presented a parathyroid adenoma, for which a study of the MEN1 gene was performed, showing a heterozygous pathogenic variant c.249_252delGTCT;p(IIe85Serfs*33) also present in the sister with a parathyroid adenoma." (PMID 37908013, 2023). "All patients had a parathyroid adenoma; however, each patient exhibited different tumour manifestations, ranging from one MEN1-associated tumour to three MEN1-associated tumours." (PMID 35900839, 2022). "In contrast to parathyroid adenomas, somatic MEN1 mutations are very infrequent in parathyroid carcinomas, but nonetheless reported." (PMID 33269427, 2021). "Although none had suspicious personal or family histories suggestive of MEN1, one patient, who had a double parathyroid adenoma at surgery, was found to have a germline MEN1 frameshift mutation." (PMID 33716975, 2021). "We report the second case of a rare association of a somatic MEN1 gene mutation in a patient with atypical parathyroid adenoma." (PMID 32411220, 2020). "Loss of heterozygosity at the MEN1 locus on chromosome 11q13 is the most common genetic aberration in parathyroid adenoma, occurring in 26.2–50.0% of cases." (PMID 30832348, 2019). "It has been shown that miRNA_24-1 is uniquely expressed in MEN1 parathyroid adenoma tissues that conserve the wild-type allele, while it is downregulated in the MEN1 parathyroid adenoma tissues with the 11q13 LOH, as well as in sporadic parathyroid adenomas." (PMID 30598042, 2018). "GPAs are genetically similar to “usual” parathyroid adenomas with regards to frequent MEN1 mutations and infrequent hyperparathyroidism 2 gene (HRPT2) mutations." (PMID 27756436, 2016). "Beckerset al.1 reported a case of PA as a part of MEN1, associated with parathyroid adenoma, prolactinoma and toxic multinodular goiter." (PMID 25210615, 2014). "In approximately 20% of sporadic parathyroid adenoma, gastrinoma, insulinoma, and bronchial carcinoid an MEN-1 mutation can be found." (PMID 21318141, 2010). "Contrary to parathyroid adenomas, parathyroid cancer rarely exhibits MEN1 mutations." (PMID 38108848, 2024). "Up to approximately 35% of parathyroid adenomas have somatic MEN1 mutations." (PMID 39056047, 2024). "Interestingly, whole-exome studies identified MEN1 mutation/inactivation as a common molecular event also in sporadic parathyroid adenomas, unraveling the occurrence of somatic MEN1 mutations in about 35–40% of investigated sporadic tumors." (PMID 39519139, 2024).
parathyroid adenomas (continued). "Finally, menin loss in seven separate parathyroid adenomas from patients with MEN1 has been reported to be associated with a reduction in the expression of the VDR when compared to both sporadic adenomas (n = 12) and normal parathyroid tissue (n = 6)." (PMID 38038882, 2024). "MEN1 gene mutations are responsible for 15%–20% of parathyroid adenoma development." (PMID 37223014, 2023). "In one study, the incidence of MEN1 mutations was found to reach up to 35% in parathyroid adenoma." (PMID 37854190, 2023). "Parathyroid adenomas from MEN1 patients with a heterozygous MEN1 mutation are also reported to have reduced MEN1 mRNA levels, lack menin expression and overexpress miR-24-1, despite the presence of one WT MEN1 allele." (PMID 35900839, 2022). "Sporadic parathyroid adenomas frequently exhibit somatic biallelic inactivation of the MEN1 tumor suppressor gene." (PMID 40362680, 2025). "Syndromic MEN1 parathyroid adenomas therefore consist of multiple clones with subclones, which supports the current concept of the novel WHO classification of parathyroid tumors (2022)." (PMID 38244045, 2024). "Here, we analyzed histomorphology and protein expression of Menin and p27 in parathyroid adenomas of 25 patients of two independent, well-characterized MEN1 cohorts." (PMID 38244045, 2024). "Genetic analysis of 14 MEN1 parathyroid adenomas revealed evidence of monoclonality as evidenced by allelic loss." (PMID 38244045, 2024). "The identification of multiple DP-NETs and parathyroid adenomas prompted the suspicion of MEN1, resulting in a referral for genetic testing in July 2010." (PMID 39104820, 2024). "CYP24 inhibits PTH secretion by repressing PTH transcription, and CYP24 is downregulated in MEN1 mutant parathyroid adenomas." (PMID 39336822, 2024). "MEN4 can mimic MEN1, and CDKN1B mutations are implicated in the development of parathyroid adenomas as well." (PMID 38244045, 2024). "Syndromic parathyroid adenomas constitute ~ 10% of cases, found in MEN1, MEN2, MEN4, HPTJT, and isolated familial hyperparathyroidism (FIHP)." (PMID 38108848, 2024). "First, although we study a large cohort of MEN1 parathyroid adenomas from two academic centers, our study relies mainly on archived FFPE material." (PMID 38244045, 2024). "Truncating mutations of the MEN1 gene are the most frequent, together with LOH at the 11q13 locus, which has been reported in about 40% of sporadic parathyroid adenomas." (PMID 39519139, 2024). "Men1 conditional heterozygous mice, whose Men1 exons 1 and 2 were deleted to resemble MEN1 syndrome, developed parathyroid hyperplasia by 9 months of age, and Men1 conventional mice developed parathyroid adenomas by 15 months." (PMID 39409111, 2024). "MEN1 is an autosomal dominant hereditary syndrome with high penetrance that more frequently includes parathyroid adenoma and very uncommonly PC." (PMID 37834940, 2023). "In this group of patients, PHPT was diagnosed before the establishment of MEN1 diagnosis and were therefore managed as sporadic parathyroid adenomas before being referred to our institution." (PMID 35407574, 2022). "Surgery is considered the treatment of choice, and the surgical approach differs from sporadic parathyroid adenomas, since involvement of more than one parathyroid gland is the characteristic feature of MEN1-related PHPT." (PMID 35407574, 2022). "According to various studies, CDC73, MEN1, CCND1, and RET were shown to be parathyroid adenoma susceptible genes." (PMID 35879975, 2022). "The target-PPI included differentially methylated genes as well as parathyroid adenoma susceptible genes (CDC73, MEN1, CCND1, RET)." (PMID 35879975, 2022). "One study evaluated parathyroid adenomas in MEN1 and suggests three main dysregulated microRNA: miR-1301, miR-4258 and miR-664." (PMID 33716975, 2021).